MYC (MYC proto-oncogene, bHLH transcription factor)
Diseases named in the same sentence as MYC in open-access papers (continued):
Sharing a sentence is not in itself a finding about the gene and the disease.
breast cancer (continued). "To directly evaluate the potential association between FBXO28 expression and the expression of MYC target genes in breast cancer, we extracted gene expression data representing 327 clinical breast cancer specimens (; GSE6532) and identified 102 genes highly related to FBXO28 expression." (PMID 23776131, 2013). "MYC is located in the human chromosome 8q24 region, a 2 MB segment of chromosome 8 that contains susceptibility loci for several diseases including colorectal, ovarian, thyroid, prostate and breast cancer." (PMID 23145106, 2012). "Deregulated expression of the MYC oncogene, which encodes c-Myc, occurs in about 30% of human cancers, including a substantial fraction of many commonly occurring cancers such as colon, prostate, liver and breast carcinomas." (PMID 20300622, 2010). "Moreover, it has also been shown that MYC contributes to tumor progression in BRCA1-associated breast cancers and that it was gained or amplified in 53% of cases." (PMID 17417968, 2007). "Examination of the protein–protein interaction networks suggested that the correlation of TGFB2-related markers could potentially complement the PAM50 signature in the assessment of OS prognosis in breast cancer patients following validation of the TGFB2/EGFR/MYC protein associations in tumors." (PMID 41373732, 2025). "Furthermore, c-MYC aberrations is tightly associated with the prevalence of breast cancer." (PMID 36721232, 2023). "The high ATAD2 expression in breast cancer (BC) is caused by 8q24 amplification, which is closely related to the activation of multiple MYC pathways." (PMID 36008934, 2022). "Moreover, MYC deregulation plays a critical role in cell proliferation and tumor progression, and it has been associated with an aggressive clinical behavior and poor prognosis in breast cancer." (PMID 33059724, 2020). "Another major oncogene, MYC, is known to have multiple roles in metabolic regulation including cellular adaptations following endurance exercise training, but is frequently overexpressed in breast cancer cells, including MCF7 cells, and associated with poor prognosis." (PMID 32010625, 2019). "Therefore, it will be important to evaluate if a similar approach could be employed to personalise therapy in ATM-deficient MYC overexpressed breast cancers." (PMID 30746633, 2019). "In conclusion, we provide phenotypic evidence to support the hypothesis that cancers of glandular ancestry, particularly breast cancer, represent the end result of pre-existing metabolic perturbations associated with a MYC-induced systemic condition: Cancer as a metabolic epiphenomenon." (PMID 30167086, 2018). "In the MCF-7 network, MYC is a broad domain node and connected to multiple enhancer and super enhancer nodes, one of which harbors rs1121946 SNP that is in high linkage disequilibrium (LD) with index SNP rs11780156 (r2 > 0.7), a known breast-cancer associated variant." (PMID 29089515, 2017). "Our results showed that MYC overexpression was associated with worse prognosis and high risk of breast cancer, especially in patients with negative hormone receptors, which highlighted the potential of MYC as a significant prognostic biomarker of breast cancer." (PMID 29212204, 2017). "Gene MYC appeared in the list and the result is promising since MYC is a key regulator of cell growth, proliferation, metabolism, differentiation, and apoptosis and MYC deregulation contributes to breast cancer development and progression and is associated with poor outcomes." (PMID 23874497, 2013). "On the other hand, H19 can promote breast cancer cell proliferation, metastasis, and cell cycle progression by expressing miR-675, interacting with MYC protein, or taking part in the ceRNA regulatory network." (PMID 41614928, 2026). "Amplification of the 8q24 region, leading to elevated c‐MYC expression, is commonly observed in neuroblastoma, melanoma and breast cancer." (PMID 40525649, 2025).
breast cancer (continued). "As described in neuroblastoma, but also in lung carcinoma, lymphoma, and breast cancer, MYC hyperactivation can enhance tumor cell survival and proliferation." (PMID 41155227, 2025). "By contrast, hsa_circ_0068631 improves MYC mRNA stability by recruiting eukaryotic translation initiation factor 4A3 (EIF4A3) in breast cancer cells." (PMID 41318550, 2025). "Although previous studies showed that specific MYC inhibitors had anticancer potential in breast cancer experimental models, this, to our knowledge, is one of the first to describe in detail the use of a protein degrader against the oncoprotein." (PMID 39875774, 2025). "In our study, FLT4 mutations were prevalent among breast angiosarcomas (n = 11, 15.1%) and did co-occur with MYC amplifications (p < 0.001), consistent with the theory that many breast angiosarcomas develop secondary to radiation for primary breast cancer." (PMID 41301029, 2025). "An older dataset from BLs had translocation breakpoints in the virus sequence–rich area near the MYC locus, agreeing with about 140 breast cancer breakpoints." (PMID 39885374, 2025). "Of note is the group of genes SP1, MYC, HEY2, E2F1, E2F2, and HES1, which are known to be associated with the KEGG breast cancer functional pathway." (PMID 40724805, 2025). "ZFHX3 loss promotes ESR1-mediated cell proliferation in ESR1-positive breast cancer cells by upregulating breast cancer stem cells and MYC transcription, and similar findings have been reported in androgen receptor-positive prostate cancer." (PMID 41413856, 2025). "While miR-32-5p’s oncogenic role is established in prostate and colorectal cancers, its regulatory interplay with c-MYC in breast cancer remains unexplored." (PMID 40711670, 2025). "To further dissect the role of circPVT1 in altered glutaminolysis of breast cancer cells we focused on c-MYC, a well-known target of miR-33a-5p known to activate at the transcriptional activity several key metabolic enzymes." (PMID 40114244, 2025). "CTNNB1 and three additional core genes form a signaling cascade with MYC, amplifying pro-proliferative signaling in breast cancer cells." (PMID 40924735, 2025). "To investigate the degradative potential of GT19630 against MYC, we tested the molecular glue’s ability to eliminate the oncoprotein in 2 breast cancer cell lines, i.e., BT-549 and CAMA1." (PMID 39875774, 2025). "Given this context, we designed and validated miRNA sponge systems capable of disrupting MYC dosage compensation in aneuploid breast cancer cells." (PMID 40940795, 2025). "Studies have shown that OTUB1 can deubiquitinate the MYC protein, making it a potential target for breast cancer treatment." (PMID 40387552, 2025). "For instance, miR159 from Arabidopsis thaliana and soybean targeted transcription factor TCF7 in breast cancer to decrease expression of the MYC oncogene and attenuated the growth of breast cancer in vitro and in vivo." (PMID 40149445, 2025). "While our study identifies c-MYC as its key effector in breast cancer, these findings collectively underscore miR-32-5p’s versatility as an oncogenic driver across malignancies, reinforcing its potential as a therapeutic target." (PMID 40711670, 2025). "The dysregulation of c-MYC, essential for proper cellular growth and development, has been correlated with the emergence and expansion of multiple cancers, including breast cancer." (PMID 40711670, 2025). "Given that c-MYC is overexpressed in approximately 70% of breast cancers, yet upstream miRNA-based regulation is poorly defined, we prioritized miR-32-5p to investigate its functional impact on this pivotal oncogene in MCF-7 cells." (PMID 40711670, 2025). "Although such comprehensive approaches extend beyond the present work, our current findings establish a solid foundation—particularly the FBXW7-mediated axis—for subsequent high-resolution studies into the miR-32-5p/c-MYC regulatory network in breast cancer." (PMID 40711670, 2025).
breast cancer (continued). "Breast cancer cells (MCF7) with stable exogenous MYC overexpression were used to assess the impact of sponge constructs on MYC regulation." (PMID 40940795, 2025). "Based on the TCGA database, we identified 119 TNBC patients among 1059 primary breast cancer cases and assessed the prognostic significance of MYC, KRAS, and CD274 (PD‐L1) mRNA expression." (PMID 41020311, 2025). "Specifically, MOF-driven acetylation of AURKB promotes the accumulation of c-MYC, thereby facilitating malignant proliferation in breast cancer cells." (PMID 40710353, 2025). "MYC is an important oncogene that is often overexpressed or amplified in a wide spectrum of cancers, including breast cancer." (PMID 40612865, 2025). "CLK play an essential role in MYC-driven tumors, and increased expression of CLK2 reduces the prognosis of MYC-amplified breast cancer patients." (PMID 40731028, 2025). "The mechanistic exploration revealed that PAX7 influences breast cancer through the Wnt/β‐catenin signalling pathway, resulting in reduced expression of β‐catenin, c‐MYC, and Cyclin D1 when PAX7 is suppressed." (PMID 40370330, 2025). "Our previous study revealed that circACTN4 is overexpressed in breast cancer tissue and is positively correlated with the expression level of MYC." (PMID 40612865, 2025). "In liver or breast cancer, the overexpression of MYC leads to increased ribosome synthesis, prominent nucleoli and an accompanying increase in cell volume." (PMID 40525649, 2025). "Our study demonstrates that MOF-mediated acetylation of AURKB at K215 enhances AURKB stability and kinase activity, thereby promoting c-MYC accumulation and supporting breast cancer cell proliferation." (PMID 40710353, 2025). "Elevated p-eIF2α has also been observed in different gastrointestinal malignancies as well as other tumor entities including pancreatic cancer, breast cancer, prostate cancer and MYC-driven lymphoma where it is partially involved in tumor progression." (PMID 40016419, 2025). "In primary breast cancer, an analysis of molecular subtypes demonstrated that MYC was more enriched in TNBC than HER2+ (33.7% vs 12.7%, p<0.01)." (PMID 40182039, 2025). "The MYC oncogenic pathway is activated in ~50–55% of breast cancers (BCs) with ~62% of TNBCs showing MYC oncogene amplification, suggesting that MYC represents an attractive, although difficult therapeutic target for TNBC." (PMID 39706891, 2025). "Together, these findings further suggest that circACTN4 promotes breast cancer cell cycle progression and oncogenesis via MYC-induced histone H4 acetylation." (PMID 40612865, 2025). "Our study demonstrated that MYC expression was relatively high in TNBC patients compared to other types of breast cancer in the METABRIC." (PMID 40282497, 2025). "Previous study reported that ZFHX3 is involved with proliferation of breast cancer cells by enhancing MYC and TBX3 transcription, which was well recapitulated in our data." (PMID 40312397, 2025). "When stratified by response groups, this positive correlation was maintained, confirming a fundamental biological relationship between MYC and DNA repair pathways in breast cancer." (PMID 41273720, 2025). "Another cytogenetic study found frequent amplification of the oncogenes c-MYC and HER2 and association of these two amplifications with higher histological grade in breast cancers among atomic-bomb survivors in Japan." (PMID 41007286, 2025). "Several researchers had revealed that CDK1 inhibition induces MYC-dependent apoptosis through a synthetic lethal interaction between CDK1 and MYC in lymphomas, hepatoblastomas, and especially breast cancers." (PMID 40040723, 2025).
breast cancer (continued). "The identification of c-MYC as a potential miR-32-5p effector in breast cancer contrasts with established targets in other malignancies, highlighting the context-dependent nature of miRNA regulation." (PMID 40711670, 2025). "In breast cancer, the Top 5 genes were MYC, EGFR, SRC, HSP90AB1, PXDNL, and the Top 4 genes are CGC drivers." (PMID 40478912, 2025). "One of the most frequently altered genes in breast cancer is amplification and overexpression of the c-MYC oncogene (hereafter referred to as MYC)." (PMID 39875774, 2025). "ZNF121 has been shown to be a c-MYC-interacting protein with functional effects on MYC and cell proliferation in breast cancer." (PMID 40241172, 2025). "While miR-32-5p is implicated in prostate, colorectal, and hematological malignancies, its role in breast cancer—particularly its regulatory interplay with c-MYC—remains unexplored." (PMID 40711670, 2025). "We have previously shown data that miR-33a-5p directly binds the c-Myc 3’-UTR abrogating c-MYC expression in breast cancer cells." (PMID 40114244, 2025). "In patients with estrogen receptor-positive (ER-positive) breast cancer, MYC target scores were significantly correlated with tumor aggressiveness and worse survival outcomes." (PMID 40980067, 2025). "While the mechanisms of MYC in promoting breast cancer, including TNBC, have been extensively investigated, its role in normal mammary gland development requires further elucidation." (PMID 40862719, 2025). "Elevated expression levels of USP28 are observed in colon and breast carcinomas, and the stabilization of c‐MYC by USP28 is critical for tumor cell proliferation." (PMID 40227962, 2025). "These notably include MYC, an oncogenic transcription factor with a pivotal role in breast cancer progression and whose amplification and overexpression is a marker of aggressive and invasive breast cancer." (PMID 38076897, 2024). "As a major oncogene, MYC expression is regulated at transcriptional, post transcriptional and translational levels across all subtypes of breast cancers." (PMID 38965558, 2024). "Our research investigated the impact of miR-561-3p on the expression of ZEB1, HIF1A and MYC in breast cancer cells for the first time." (PMID 38462658, 2024). "This joint high prevalence is consistent with MYC and RAD21 being closely linked on amplicon 8q24 and frequently coamplified in BRCA1-mutated breast cancer." (PMID 38869771, 2024). "MYC stimulates fatty acid synthesis in prostate, colon, and breast cancers, and MYC upregulates several TCA cycle genes to produce the fatty acid precursor, citrate." (PMID 37450923, 2024). "In breast cancer, MYC promotes this interaction through extracellular vesicles (EVs) containing miR-105 transported from cancer cells to CAFs." (PMID 38390324, 2024). "FGF2 can activate the ERK1/2 pathway and elevate MYC levels to reduce sensitivity to endocrine therapy and facilitate tumor growth in patients with breast cancer." (PMID 38764020, 2024). "It has been reported that the expression of COPS5 is a prerequisite for the MYC activity in breast cancer." (PMID 38974382, 2024). "In ER+ breast cancer cells, MYC expression is predominantly driven by estrogen signaling and is a direct transcriptional target of ERα." (PMID 38965558, 2024). "This is accompanied by de novo enhancer-promoter interactions correlating with not only elevated MYC expression in T1 and C1 cells, but also with enhanced expression of other breast cancer related genes on both chromosomes." (PMID 38076897, 2024). "Several immune pathways are regulated by MYC to attack or eliminate carcinomas, such as prostate, colon, lung, and breast cancers." (PMID 37450923, 2024). "To test it, we measured the expression of RB1 and MYC in bladder, prostate and breast cancer cell lines and found that pRB1 protein levels were negatively correlated with MYC expression." (PMID 38424044, 2024).
breast cancer (continued). "UNC0642 is a G9a catalytic inhibitor in which the anti-proliferative response to UNC0642 correlates with MYC sensitivity and gene signatures in breast cancer cell lines." (PMID 38547242, 2024). "MYC deregulation is involved in the development of a wide variety of cancers, BCL2 is dysregulated in many malignancies including breast cancer and gastric carcinoma, and NF-κB is implicated in numerous cancers." (PMID 38965209, 2024). "Conversely, LINC00460 transcription is directly activated by c-MYC and forms a positive feedback loop in breast cancer cells, driving resistance to tamoxifen." (PMID 39372872, 2024). "Another specific example is miR-105, which is secreted by breast cancer cells in EVs and has been implicated in mediating metabolic reprogramming of CAFs through MYC signalling and contributes to breast cancer growth." (PMID 38794316, 2024). "In breast cancer cells, elevated mTOR/c-MYC was previously shown to increase the expression of OGT and O-GlcNAcylation." (PMID 39388284, 2024). "For example, highly selective ERβ agonists can attenuate the viability of breast cancer cell lines in vitro, and ERβ activation has also been observed in prostate cancer to inhibit tumor cell proliferation and suppress MYC proto-oncogene transcription." (PMID 38641065, 2024). "MYC is a crucial oncoprotein that significantly impacts the altered signaling pathways in cancer cells, including breast cancer." (PMID 39408832, 2024). "In breast cancer, focal MYC amplification is relatively rare (~6% in The Cancer Genome Atlas (TCGA) and the International Cancer Genome Consortium cohorts), whereas arm-level amplification of 8q is common (~50%)." (PMID 38388848, 2024). "Notable exceptions include cytobands 8q24.21 (in TNBC) and 11q13.2–5 (in luminal), which harbor prevalent breast cancer oncogenes MYC and CCND1, respectively, and are frequently amplified." (PMID 38260372, 2024). "Rather, the BCMP organoid data and the MYC amplified PDxO models provide supporting evidence that MYC amplified breast cancers can be highly sensitive to this therapeutic approach." (PMID 38001268, 2024). "USP22 and USP36 regulate the cellular turnover of c-MYC in breast cancer, and c-MYC expression is stabilized by USP28 and USP37 in colon carcinoma and lung cancer, respectively." (PMID 39664521, 2024). "These PDOs are often enriched for luminal progenitor (LP)-like cells, showing gene signatures reminiscent of aggressive MYC-driven, basal-like breast cancers." (PMID 38791938, 2024). "Kaplan–Meier analysis showed that higher expression of each of MYC and JAG1 is associated with shorter breast cancer patient relapse-free survival, underlining their oncogenic roles in human breast cancer." (PMID 38886396, 2024). "In drug-resistant breast cancer MYC is overexpressed, glutamine transporter proteins SLC1A5 and GLS are upregulated, and glutamate metabolism is markedly enhanced to promote proliferation of drug-resistant tumor cells." (PMID 39027328, 2024). "Because of its potent reduction of tumor burden, Omomyc stands as the first direct MYC inhibitor to ascend in dose-escalated phase 1 and phase 2 clinical trials of patients with non-small cell lung, colorectal, and breast cancer (NCT04808362)." (PMID 38390324, 2024). "A previous study revealed that chronic stress-induced epinephrine promoted the deubiquitylation of MYC by USP28 via lactate dehydrogenase A (LDHA)-dependent metabolic reprogramming in breast cancer." (PMID 38689092, 2024). "MYC is amplified or overexpressed in ~35% of breast cancers and exerts pleiotropic effects across the genome." (PMID 39545637, 2024). "MYC regulates the self-renewal ability of CSCs, as MYC is a target of the Wnt/β-catenin pathway that is linked to CSC self-renewal in several solid tumors, such as colon and breast cancers and gliomas." (PMID 39547513, 2024). "BRCA1, MYC and IL-6 were identified as the top three hub genes in infected-breast cancer cells based on the connectivity of PPI analysis." (PMID 38654350, 2024).